MTA2 (metastasis associated 1 family member 2)
Diseases named in the same sentence as MTA2 in open-access papers (continued):
Sharing a sentence is not in itself a finding about the gene and the disease.
osteosarcoma (2 papers, 2015 to 2024). A usually aggressive malignant bone-forming mesenchymal neoplasm, predominantly affecting adolescents and young adults. "Our results show that MTA2 was elevated in osteosarcoma cell lines and osteosarcoma tissues and was associated with tumor stage and overall survival of osteosarcoma patients." (PMID 39248711, 2024). "To further understand the molecular mechanism underlying the role of MTA2 in osteosarcoma metastasis, we performed human proteinase analysis in MTA2-depleted osteosarcoma cells." (PMID 39248711, 2024). "The possible transcription and translation mechanisms underlying ERK-mediated metastasis of osteosarcoma cells inhibited by MTA2 are under investigation." (PMID 39248711, 2024). "Overall, these findings suggest that uPA may be a biomarker for osteosarcoma and that involved in the molecular mechanism underlying of the involvement of MTA2 in human osteosarcoma metastasis." (PMID 39248711, 2024). "Using a loss-of-function assay, we assess the effects of MTA2 depletion on osteosarcoma cell metastasis in vitro and in vivo with the goal of determining whether MTA2 is a potential therapeutic target for osteosarcoma." (PMID 39248711, 2024). "Taken together, our findings suggest that MTA2 plays a critical role in human osteosarcoma metastasis." (PMID 39248711, 2024). "To determine the effect of MTA2 on the progression of metastasis in osteosarcoma in vivo, we introduced MTA2-depleted 143B cells with lentiviral infection into mice." (PMID 39248711, 2024). "Knockdown of MTA2 inhibited osteosarcoma cell migration and invasion by reducing the expression of urokinase-type plasminogen activator (uPA)." (PMID 39248711, 2024). "Our result revealed that MTA2 inhibited osteosarcoma metastasis via activation of ERK1/2-inhibited uPA signaling." (PMID 39248711, 2024). "In summary, MTA2 depletion decreased osteosarcoma cell migration and invasion by inducing the ERK1/2 phosphorylation-mediated uPA pathway." (PMID 39248711, 2024). "Our study findings are consistent with these other studies, suggesting that MTA2 depletion decreased the metastatic capacity of osteosarcoma cells by inhibiting uPA expression." (PMID 39248711, 2024). "Overall, our study suggests that MTA2 knockdown suppresses osteosarcoma cell metastasis by decreasing uPA expression via ERK signaling." (PMID 39248711, 2024). "Analysis of data in TCGA using the TNMplot software showed that the MTA2 protein level was significantly higher in osteosarcoma tissue than in normal tissue (P < 0.001)." (PMID 39248711, 2024). "To examine the clinical significance of MTA2 in human osteosarcoma patients, we analyzed MTA2 expression in a human osteosarcoma tissue array." (PMID 39248711, 2024). "Compared to normal tissues, MTA2 protein expression was upregulated in osteosarcoma tumor tissue (P < 0.01)." (PMID 39248711, 2024). "This study aims to elucidate the clinical significance, underlying molecular mechanisms, and biological functions of MTA2 in human osteosarcoma in vitro and in vivo." (PMID 39248711, 2024). "Bioinformatic analysis demonstrated that high levels of uPA in human osteosarcoma tissues correlated positively with MTA2 expression." (PMID 39248711, 2024). "In vivo animal experiments revealed that MTA2 depletion reduced the metastatic potential of osteosarcoma cells, as indicated by a decrease in the number of metastatic nodules." (PMID 39248711, 2024). "The present study is the first to report the overexpression of MTA2 in osteosarcoma tissues, and its correlation with tumor stage and survival rates of osteosarcoma patients." (PMID 39248711, 2024). "However, the relationship between MTA2 and uPA expression and their effects on the metastatic behavior of osteosarcoma are unclear." (PMID 39248711, 2024). "We observed elevated levels of MTA2 expression in 4 osteosarcoma cell lines." (PMID 39248711, 2024).
osteosarcoma (continued). "We found that uPA expression was higher in osteosarcoma tissues than in normal tissue and correlates positively with MTA2 expression, suggested that uPA may be useful as a predictive or prognostic biomarkers for osteosarcoma progression." (PMID 39248711, 2024). "To investigate whether ERK1/2 signaling acts downstream of MTA2, we first examined the role of ERK1/2 activation in MTA2-depleted osteosarcoma cells." (PMID 39248711, 2024). "The present study aims to determine whether MTA2 is overexpressed in human osteosarcoma tissues and cells and whether MTA2 expression levels correlate with clinical data and overall survival rates of osteosarcoma patients." (PMID 39248711, 2024). "Furthermore, treatment with recombinant human uPA (Rh-uPA) caused significant restoration of OS cell migration and invasion in MTA2 knockdown osteosarcoma cells." (PMID 39248711, 2024). "Furthermore, MTA2 expression was greater in osteosarcoma tissue of stages II (IIA+IIB) and III than in that of stage I (P < 0.01)." (PMID 39248711, 2024). "Therefore, our findings indicate that MTA2 overexpression promotes osteosarcoma progression." (PMID 39248711, 2024). "Moreover, our in vitro study results revealed high levels of MTA2 expression in osteosarcoma cells." (PMID 39248711, 2024). "The relationship between metastasis-associated protein 2 (MTA2) overexpression and tumor growth and metastasis has been extensively studied in a variety of tumor cells but not in human osteosarcoma cells." (PMID 39248711, 2024). "Western blot assay results show that MTA2 knockdown induced ERK1/2 phosphorylation in both osteosarcoma cell lines, with no change in the total ERK1/2 protein level." (PMID 39248711, 2024). "We also must consider whether the uPA receptor (uPAR) is regulated by MTA2; accordingly, further studies will investigate the regulatory roles of the uPA/uPAR/ERK signaling pathway in osteosarcoma progression." (PMID 39248711, 2024). "Treatment with Rh-uPA protein restored the osteosarcoma cell migration (shMTA2-HOS cells, 167.3% increase; shMTA2-143B cells, 114.5% increase) and invasion (shMTA2-HOS cells, 141.2% increase; shMTA2-143B cells, 122.5% increase) by MTA2 depletion, compared with shMTA2-OS cells." (PMID 39248711, 2024).
renal carcinoma (2 papers, 2019 to 2024). A carcinoma arising from the epithelium of the renal parenchyma or the renal pelvis. "The inhibition of MTA2 expression in human renal cancer cells decreases their invasiveness and metastasis through the miR-133b/MMP9 pathway." (PMID 39248711, 2024).
acute myeloid leukemia (1 paper, 2024). Acute myeloid leukemia (AML) is a group of neoplasms arising from precursor cells committed to the myeloid cell-line differentiation. "Additionally, we evaluated GeneCompass by in silico deleting more transcription factors (TFs) in various cell types of different species, i.e., STAT1 on human PBMC cells, SMARCA4 on human acute myeloid leukemia cells, CBX8 on mouse embryonic stem cells, and MTA2 on mouse colonic epithelium cells." (PMID 39375485, 2024).
adenoma (1 paper, 2015). A neoplasm arising from the epithelium. "As a result of K-means clustering, the expression levels of five genes, AKT1, BCL2L1, ERBB2, MTA2 and TNFRSF25, were found to be significantly up-regulated (p < 0.05) in LST-adenoma, compared to Ip-adenoma." (PMID 26048755, 2015). "By K-means clustering, the expression levels of five genes, AKT1, BCL2L1, ERBB2, MTA2 and TNFRSF25, were seen to be significantly up-regulated (p <0.05) in LST-adenoma compared to Ip-adenoma." (PMID 26048755, 2015).
adrenocortical carcinoma (1 paper, 2023). "Analysis of MTA2 mutations in pan-cancer in the cBioPortal database revealed that MTA2 was amplified in cholangiocarcinoma, adrenocortical carcinoma, ovarian serous cystadenocarcinoma, liver hepatocellular, mesothelioma, pheochromocytoma, paraganglioma, and lung squamous cell carcinoma." (PMID 37371463, 2023).
autoimmune disease (1 paper, 2023). A disorder resulting from loss of function or tissue destruction of an organ or multiple organs, arising from humoral or cellular immune responses of the individual to their own tissue constituents. "Furthermore, inactivation of MTA2 leads to abnormal T-cell activation and lupus-like autoimmune disease in mice." (PMID 37371463, 2023).
brain glioma (1 paper, 2017). A malignant glioma that involves the brain. "While in human brain glioma cell lines, knockdown of MTA2 expression was found to could significantly suppress tumor cell growth, migration and invasion." (PMID 28418887, 2017).
cervical tumors (1 paper, 2021). "Interestingly, MMP12 expression was significantly correlated with MTA2 expression in cervical tumors (P = 0.001)." (PMID 33958583, 2021).
dermatomyositis (1 paper, 2016). Dermatomyositis (DM) is a type of idiopathic inflammatory myopathy characterized by evocative skin lesions and symmetrical proximal muscle weakness. "The NuRD multiprotein complex includes the dermatomyositis-specific Mi2 autoantigen (Mi2-β), RB-associated proteins 46 and 48 (RbAp46 and RbAp48), MBD2 and MBD3, and metastasis-associated proteins 2 and 3 (MTA2 and MTA3)." (PMID 26810492, 2016).
Hypercalcemia (1 paper, 2022). An abnormally increased calcium concentration in the blood. "Low MTA2 levels were associated with hypercalcemia among patients with NDMM (p = 0.031)." (PMID 36454786, 2022).
kidney clear cell carcinoma (1 paper, 2019). "MTA2 expression was examined through immunohistochemical (IHC) staining using a human kidney clear cell carcinoma tissue array procedure." (PMID 31771219, 2019).
leukemia (1 paper, 2023). A malignant (clonal) hematologic disorder, involving hematopoietic stem cells and characterized by the presence of primitive or atypical myeloid or lymphoid cells in the bone marrow and the blood. "In the leukemia cell lines tested, MTA3 is not expressed and MTA2 is a mild dependency." (PMID 36707513, 2023).
myeloma (1 paper, 2022). "On the other hand, among patients with MM (NDMM and RRMM), the MTA2 protein was localized in both the nucleus and cytoplasm of myeloma cells." (PMID 36454786, 2022). "Accumulations of MTA2 and AGO2 in the cytoplasm of myeloma cells were observed in the BM samples collected at NDMM and RRMM." (PMID 36454786, 2022).
renal cell carcinoma (1 paper, 2019). "However, the role of MTA2 in the progression of renal cell carcinoma (RCC) has not yet been delineated." (PMID 31771219, 2019).
schizophrenia (1 paper, 2025). A major psychotic disorder characterized by abnormalities in the perception or expression of reality. "ROC analysis showed that five genes—MALAT1, PPIL3, ITM2A, MTA2, and GJA1—effectively distinguished schizophrenia from controls (AUC >0.70)." (PMID 41199749, 2025). "Correlation analysis linked OXPHOS scores positively with PPIL3 and ITM2A, negatively with MALAT1 and GJA1, and not significantly with MTA2, suggesting their role in schizophrenia-related mitochondrial dysfunction." (PMID 41199749, 2025).
tumor (45 papers, 2010 to 2026). "Overexpression of circMTA2 was highly associated with tumor progression by upregulating MTA2 protein levels in GC cells." (PMID 38474064, 2024). "Studies have demonstrated that MTA2 is highly expressed in many types of cancers and is associated with tumor formation and progression." (PMID 38474064, 2024). "MTA2, a member of the metastatic tumor-associated transcriptional regulator family, is a core component of the nucleosome remodeling and histone deacetylation complex." (PMID 37371463, 2023). "MTA2 is a member of the metastasis-associated gene family is reportedly closely associated with tumor progression 36-38." (PMID 36741260, 2023). "Multiple clinical trials are currently being conducted which are focused on PRMT5 or MTA2 inhibition designed to take advantage of the high intracellular arginine levels in the MTAP deficient tumor cells." (PMID 35881043, 2022). "Metastasis-associated protein 2 (MTA2) is a transcriptional regulator belonging to the metastasis tumor-associated family." (PMID 33958583, 2021). "For example, miRNA-589 functions as a tumor inhibitor via directly targeting metastasis-associated protein 2 (MTA2) in BC27." (PMID 32811810, 2020). "MTA2 is a member of the metastatic tumor-associated family of transcriptional regulators, and plays a central role in cytoskeletal organization and motility pathways, which are essential processes in the metastatic cascade." (PMID 31645899, 2019). "MTA2 overexpression has been observed in several human cancers and is associated with tumour invasion capacity, metastasis, and poor prognosis." (PMID 31771219, 2019). "Increased MTA2 expression was significantly associated with tumour grade (p = 0.002) and was an independent prognostic factor for overall survival with a high RCC tumour grade." (PMID 31771219, 2019). "Another gene, MTA2, is one of metastasis-associated tumor gene family members and was an important prognosis biomarker of CRC." (PMID 31646964, 2019). "MTA2 is a member of the metastasis-associated gene family that has been reported to be closely associated with tumor progression." (PMID 29743816, 2018). "In addition, MTA2 expression was associated with Tumor Mutation Burden (TMB) in 12 cancer types and MSI in 8 cancer types." (PMID 37371463, 2023). "Metastasis-associated protein 2 (MTA2) has been linked to metastasis and tumor growth." (PMID 36905477, 2023). "The miR-1236-3p-MTA2 axis provides insight into the mechanisms underlying tumor metastasis, and may serve as a promising therapeutic target for GC treatment." (PMID 29743816, 2018). "The involvement of FEN1, ZBTB3, and MTA2 in controlling genomic stability suggests that functional dysregulation of these genes through mutations would facilitate further tumor mutagenesis, raising the possibility of these oncogenes as potential therapeutic targets for ESCC patients." (PMID 29348864, 2017). "Accumulating evidence suggests that MTA2 is frequently amplify in several types of cancers, closely associates with tumor cells migration and invasion, relates to the malignant characteristics and poor prognosis, which therefore has been considered as playing tumor oncogenic roles." (PMID 41159000, 2025). "Metastasis-associated protein 2 (MTA2) is a central component of the Mi-2/nucleosome remodeling and deacetylase (NuRD) complex and precisely controls cytoskeleton reorganisation at the transcriptional level; moreover, it is closely associated with tumour progression and metastasis." (PMID 31771219, 2019). "Among emerging targets, metastasis-associated protein 2 (MTA2) is overexpressed in PDAC and promotes tumor progression partly by repressing PTEN transcription, thereby fueling PI3K/AKT hyperactivation." (PMID 40943389, 2025). "Here, we mainly review in the current research the status of MTA2 and its implications in normal development and various tumor biology." (PMID 41159000, 2025).
tumor (continued). "Here, we developed an AS1411 aptamer-functionalized liposomal platform encapsulating siRNA against metastasis-associated protein 2 (MTA2), a chromatin remodeling factor that suppresses the tumor suppressor PTEN and activates PI3K/AKT signaling." (PMID 40943389, 2025). "We hope that this review will help tumor molecular biologists further understand the molecular mechanism of MTA2 in normal development and cancer." (PMID 41159000, 2025). "Mechanistically, circMTA2 interacted with ubiquitin carboxyl-terminal hydrolase L3 (UCHL3) to restrain MTA2 ubiquitination and stabilize MTA2 protein expression, thereby facilitating tumor progression." (PMID 38474064, 2024). "Depending on the cellular context, NuRD can promote or suppress tumorigenesis, and through the complex members MTA1 and MTA2 affect tumor progression and metastasis." (PMID 39696035, 2024). "Meanwhile, our results revealed that MTA2 was generally highly expressed in tumor tissues from the TCGA database." (PMID 37371463, 2023). "We believed that MTA2 contributed to the development of these tumors through amplification and generated a poor prognosis, suggesting that MTA2 was capable of triggering tumor progression through amplification." (PMID 37371463, 2023). "In conclusion, increasing evidence demonstrates that MTA2 is an important regulator of tumor progression and that its expression can affect the prognosis of cancer patients." (PMID 37371463, 2023). "We acquired 11,057 pan-cancer and normal samples from 33 tumor types from the TCGA database to investigate the difference in the expression of MTA2 between tumor and normal tissues." (PMID 37371463, 2023). "The results suggested that MTA2 can act as a prognostic biomarker in a variety of cancers and that MTA2 plays an essential role in tumor immunity by affecting tumor-infiltrating immune cells, TMB, and MSI." (PMID 37371463, 2023). "Based on our observations that SMYD3 and the NuRD (MTA1/MTA2) complex are physically and functionally associated, we next investigated if MTA1 or MTA2 have the same role of SMYD3 in tumor proliferation and invasion." (PMID 36575438, 2022). "Previous studies have indicated that MTA1 and MTA2 support tumor progression and EMT, while MTA3 inhibits EMT and cancer metastasis." (PMID 36575438, 2022). "Previous studies demonstrated that MTA2 plays an important role in cytoskeletal organization and transcription, as well as in the promotion of the metastatic potential of tumor cells." (PMID 33958583, 2021). "To investigate the function of the NuRD complex on the genome level, we performed ChIP-seq assays in RH4 cells for CHD4, RBBP4, HDAC2, and MTA2, as well as for the tumor driver P3F, and other relevant epigenetic regulators and histone marks." (PMID 32744500, 2020). "The MTA2-depleted MIA Paca-2 cells showed significantly weakened tumor growth ability 4 weeks after cell implantation." (PMID 30814496, 2019). "Meanwhile, xenograft tumor model study also showed that knockdown of MTA2 inhibited the tumor growth in vivo." (PMID 30814496, 2019). "In our study, MTA2 overexpression was significantly more pronounced in tumor tissues of patients ≥ 61 years of age, and in those with intestinal GC, a histologic type associated with better prognosis as compared to diffuse GC." (PMID 31645899, 2019). "By using The Cancer Genome Atlas (TCGA) database, we observed higher mRNA expression of MTA2 in tumour tissues than in normal tissues and in higher tumour grades than in lower grades." (PMID 31771219, 2019). "A high expression of MTA2 was found to be significantly correlated with only the tumor grade of HCC patients (P < 0.01)." (PMID 31777601, 2019). "In summary, our results showed that miR-1236-3p functioned as a tumor suppressor to inhibit cell invasion in GC by targeting MTA2 and inhibiting the EMT process." (PMID 29743816, 2018).